BRAF (B-Raf proto-oncogene, serine/threonine kinase)
Diseases named in the same sentence as BRAF in open-access papers (continued):
Sharing a sentence is not in itself a finding about the gene and the disease.
melanoma (continued). "Combination BRAF plus MEK inhibitors and immune checkpoint inhibitor therapy in BRAFV600 mutation-positive advanced or metastatic melanomas." (PMID 36675114, 2023). "As already demonstrated by numerous authors, when extensive molecular tests were available, most of the tumors discussed in this review carry mutations typical for melanomas, such as NF1, BRAF, and NRAS mutations." (PMID 37373134, 2023). "A 54-year-old female with BRAF wild-type of anal primary melanoma received adjuvant immunotherapy with nivolumab following surgical resection." (PMID 37868454, 2023). "We also performed the same combinatorial experiments in BRAF-mutant WM115 melanoma cells that are intrinsically resistant to targeted therapies." (PMID 36418472, 2023). "Both IL-17 and TH17 cell differentiation GES were among the most significantly over-represented pathways in MAPK-mutated (n = 77 BRAF hotspot-mutant, n = 42 NRAS hotspot-mutant, n = 1 NF1-mutant) melanomas compared to triple-WT melanomas (n = 36)." (PMID 37525015, 2023). "This important pathway is also involved in the intrinsic and acquired resistance to MAPKi in BRAF mutant melanoma." (PMID 37508519, 2023). "Ongoing registration phase III trials are currently evaluating newer immunotherapy combinations and the role of BRAF/MEK-directed targeted therapy for stage II melanoma." (PMID 37301717, 2023). "We show that LNP-miRs are capable of simultaneously hitting many intrinsic and extrinsic oncogenic pathways adopted by melanoma cells to survive BRAF and MEK inhibition." (PMID 36418472, 2023). "A possible reason for the lower efficacy of ICI in Asian patients with BRAF V600‐mutant melanoma is the lower UV‐induced TMB due to skin phototype, which is around type III–IV in Japanese populations according to Fitzpatrick skin phototyping." (PMID 37584204, 2023). "This is the case, for instance, in NRAS-mutated melanoma, in which RAF1 and BRAF compensate for each other, and ARAF compensates for the loss of both other isoforms in a mechanism that is still ERK-dependent." (PMID 37020037, 2023). "Recurrent rearrangements in RAF1, which are functionally similar to BRAF fusions, have been found to occur in advanced prostate cancers, gastric cancers, melanomas, and juvenile pilocytic astrocytomas." (PMID 38137485, 2023). "We initially identified oncosuppressor miR-579-3p as a novel master regulator of MAPKi resistance in BRAF-mutant melanomas." (PMID 36418472, 2023). "Altogether these findings have profound translational implications in the attempt i) to develop miRNA-targeting therapies to mitigate the metastatic phenotypes of BRAF-mutant melanomas and ii) to identify novel biomarkers able to guide clinical decisions." (PMID 38008717, 2023). "Co-treatment of BRAF-mutant melanoma cell lines with the EP300/CREBBP inhibitor I-CBP112 decreased the sensitivity of the melanoma cells to BRAFi, increasing the number of colonies formed." (PMID 38030596, 2023). "TCF12 enhances melanoma cell proliferation, metastasis, and sensitivity to BRAF(V600E)-targeted therapy." (PMID 37760480, 2023). "Metabolic consequences as a result of the inhibition of BRAF by vemurafenib have been investigated using HP [1-13C] pyruvate MRSI in melanoma cell lines." (PMID 37233647, 2023). "MEK inhibitors are often used along with BRAF inhibitors to treat a variety of cancers including melanomas." (PMID 37485446, 2023). "“WM983B BRAF inhibitor” samples indicates replicates of a vemurafenib-resistant monoclonal human melanoma cell line, WM983B E6-C614 transfected with a barcode library and treated with 250 nM vemurafenib." (PMID 36819662, 2023). "Alterations at BRAF level: BRAF splicing variation and amplification have been detected in D/T combination therapy-resistant melanoma in patients." (PMID 37834284, 2023).
melanoma (continued). "In fact, BRAF inhibitors have demonstrated antitumor activity in clinical trials on patients with BRAF mutant malignancies, such as melanoma, and one case report described a case of a GIST that experienced tumor regression with dabrafenib." (PMID 37046734, 2023). "Nevi display senescence signature and rarely develop into melanomas, presumably because aberrant BRAF signaling induces a growth arrest response longer than expected." (PMID 37762344, 2023). "Due to the frequent activating mutation of the BRAF gene, the constitutive activation of the RAS-RAF-MEK-ERK signalling is very common in melanoma." (PMID 37790750, 2023). "In this study, we specifically focused on vemurafenib as the first FDA-approved BRAF inhibitor used in treatment of advanced malignant melanoma." (PMID 37509693, 2023). "High expression was associated with BRAF mutation and significantly correlated with poorer DFS, melanoma-specific survival and OS." (PMID 37568798, 2023). "While immunotherapy (ICI) can be administered independent of mutational status, BRAF and MEK kinase inhibitors represent another effective treatment option for patients with BRAF mutant melanoma." (PMID 37543586, 2023). "For instance, the therapeutic responses of BRAF-mutant cancers to these inhibitors ranged from a response rate of 48% in melanoma to 5% in colorectal cancer." (PMID 36624452, 2023). "Approved therapies for melanoma are often unsuccessful because resistance to BRAF and MAPK pathway inhibitors occurs." (PMID 37189846, 2023). "In one study in BRAF-resistant melanoma, it was found that a combination of MEK inhibitor with PI3K inhibitor led to tumoricidal effects." (PMID 37231247, 2023). "BRAF and NRAS mutations in the MAPK signaling pathway are found in about half of all melanoma cases, resulting in constitutive activation of the MAPK pathway." (PMID 36747120, 2023). "Targeted therapies, including BRAF and MEK inhibitors, are valuable treatment options for patients with unresectable or metastatic BRAF V600-mutant melanoma." (PMID 37706179, 2023). "In particular, oncogenic BRAF mutations, including the most frequent, BRAFV600E, have been widely described in melanomas and are associated with poor prognosis." (PMID 37298104, 2023). "RAD51 staining showed that healthy fibroblasts raise the number of RAD51 foci after blocking the NHEJ-related protein DNA-PK, assuming a proficient HR pathway, as well as in the BRAF wildtype melanoma cell line LIWE." (PMID 36229655, 2023). "Mir222-5p was analyzed as an important factor in melanoma progression, resistance against BRAF and as a prognostic factor." (PMID 36982460, 2023). "KIT mutation (19.1–23.1%) was the most frequently found driver mutation in mucosal melanomas followed by NF1 (7.8–16.4%), RAS (6.2–17.9%), and BRAF (3.1–16.4%) mutations." (PMID 37239381, 2023). "Accordingly, the mTOR inhibitor everolimus is able to overcome the resistance of BRAFV600E melanoma cells to BRAF and MEK inhibition." (PMID 37174072, 2023). "Findings from this study indicate that BRAFV600E mutant melanoma cells respond to BRAF inhibition-induced stress by secreting factors that enable the survival of vemurafenib-sensitive cells and facilitate the growth of vemurafenib-resistant clones." (PMID 37106808, 2023). "Further research should investigate the factors causing these discrepancies and the feasibility of using other molecular markers with BRAF status to better stratify patients for melanoma treatment." (PMID 38003476, 2023). "During the last decades, the molecular characterization of this tumor has revealed the existence of four subtypes, namely BRAF mutated, NRAS mutated, NF1 mutated and triple wild type melanomas, respectively." (PMID 38008717, 2023). "BRAF fusions are reported in 3% (14/531) of melanomas, 2% (3/1062) of gliomas, and approximately 1% of non-small cell lung carcinomas (NSCLCs) and colorectal cancers." (PMID 38137485, 2023).
melanoma (continued). "For example, triple therapy of PD-L1 inhibitor atezolizumab plus BRAF inhibitor vemurafenib and MEK inhibitor cobimetinib has been approved as the first-line treatment in advanced melanoma patients with BRAFV600 mutations." (PMID 37345194, 2023). "BRAF is a serine/threonine protein kinase which activates the MAP kinase/ERK-signaling pathway and approximately 50% of cutaneous melanomas are found to have BRAF V600 somatic mutations." (PMID 36836846, 2023). "This is also supported by our in silico findings (GSE50509), which show comparable expression levels of PLK1 in progressive melanomas during treatment with BRAF inhibitors compared to the time before treatment." (PMID 36768289, 2023). "KEYNOTE 054 and CHECKMATE 238 also brought anti‐PD1 blockade immunotherapy to the adjuvant setting for both BRAF‐mutant and wide‐type melanoma." (PMID 37016119, 2023). "In summary, risk of disease progression following cessation of treatment is high in adult patients with BRAF V600–positive melanoma." (PMID 37124503, 2023). "We extended our analyses to additional oncogenic BRAF and BRAFwt/NRASwt melanoma syngeneic models and confirmed SNAI1 reactivation in the stroma of these tumours." (PMID 37516803, 2023). "In this work, we show that Cdc42(G12V) drives cancer phenotypes in BRAF mutant A375 melanoma cells, including proliferation, anchorage-independent growth, migration, and invasion." (PMID 37114375, 2023). "Results in clinical trials of targeted therapy with BRAF/MEK inhibition plus anti-PD-1 therapy in patients with BRAF-mutant melanoma have been inconsistent." (PMID 37507765, 2023). "BRAF inhibitors have shown significant clinical activity against BRAFV600E-mutated tumor types like non-small cell lung cancer and melanoma." (PMID 38202120, 2023). "PET-16 was found to reduce levels of mutant BRAF in melanoma as it synergized with the BRAF inhibitor PLX4032 by enhancing the durability of response to BRAF inhibition in vivo." (PMID 37189349, 2023). "The thiazole benzenesulfonamide 13 (HA15) was identified as a Grp78 inhibitor that enhanced ER stress associated with autophagy and apoptosis, leading to cell death in melanoma cells, in particular in BRAF-mutant cells, at a concentration of 10 μM." (PMID 36835501, 2023). "Our analyses of an inducible BRAF-driven melanoma reporter model reveal that SNAI1 in melanoma is reactivated in the stroma, particularly in CAFs." (PMID 37516803, 2023). "In our present study, we introduced a patient-derived tumor xenograft model from a BRAF V600E mutant melanoma patient, with high intratumoral heterogeneity and microenvironment characteristics." (PMID 37508582, 2023). "Taken together, these data identify a novel, clinically actionable and well-tolerated combination treatment that effectively delays the occurrence of resistance and dramatically increases progression-free survival in BRAF mutant melanoma." (PMID 37072838, 2023). "Somatic BRAF mutations are found most frequently in skin with low cumulative solar damage (CSD), which predominately present as superficial spreading melanomas." (PMID 37841001, 2023). "In melanoma patients undergoing treatment with BRAF inhibitors (BRAFi), WNT5A expression in tumor tissues correlates with therapy response." (PMID 36982422, 2023). "Overall, these results suggest co-regulation of the IL-17 and the MAPK pathway, particularly in BRAF-mutant melanomas in which there is strong MAPK activation." (PMID 37525015, 2023). "A 78-year-old male with a history of large granulocytic leukemia (LGL) with chronic pancytopenia presented with wild-type BRAF melanoma of the right cheek." (PMID 37338166, 2023). "The clinical management of metastatic melanoma has been changed by BRAF (BRAFi) and MEK inhibitors (MEKi), which represent a standard treatment for BRAF-mutant melanoma." (PMID 36830931, 2023). "Here we provide data indicating that epigenetic suppression of PGC1α defines an aggressive subset of chronic BRAF-inhibitor treated melanomas." (PMID 37277330, 2023).
melanoma (continued). "NRAS and BRAF are altered in melanoma (17% and 55%, respectively), thyroid carcinoma (19% and 55%, respectively), and lung cancer (1% and 5%, respectively)." (PMID 37370689, 2023). "The highest mutation frequency of BRAF, ATRX, IDH1, CDKN2A, and EGFR was seen in melanoma (SKCM), thyroid carcinoma (THCA), brain lower-grade glioma (LGG), head and neck squamous cell carcinoma (HNSC), and glioblastoma multiforme (GBM), respectively." (PMID 37000317, 2023). "Increased the relative abundance of Bacteroides spp. led to the inhibition of BRAF mutant melanoma growth and enhanced the efficacy of a MEK inhibitor against melanoma." (PMID 37458148, 2023). "In melanoma, CDKN2A mutations are often found in combination with other genetic changes, such as BRAF mutations." (PMID 37504268, 2023). "A positive predictive value for BRAF mutant melanoma with ICI corresponds well to our data indicating that BRAF mutant melanoma and even more if additional TMB-high, had the best RFS." (PMID 35192052, 2023). "Trametinib acts as an a BRAF/mitogen-activated protein kinase kinase (MEK) inhibitor and is approved for the adjuvant treatment of melanoma with BRAFV600E or −V600K mutations." (PMID 37287694, 2023). "Type I inhibitors are not indicated for the treatment of patients with BRAF wild-type melanoma or melanomas harboring oncogenic BRAF fusions." (PMID 37219686, 2023). "BRAF inhibitors (BRAFis) represent a significant advancement in melanoma treatment; however, their effectiveness is limited by rapid resistance emergence." (PMID 38104141, 2023). "One recent study introduced a mathematical model of plasticity-mediated drug resistance of melanoma treated with BRAF/MEK inhibitors." (PMID 36952376, 2023). "Other studies have shown that NR4A1 is induced by oncogenic serine/threonine-protein kinase B-raf (BRAF) in melanoma cells and is involved in promoting the proliferation, survival, and invasiveness of melanoma cells." (PMID 39872303, 2023). "Altogether, the findings indicate that AR overexpression in melanoma cells effectively counteracts growth suppression by BRAF inhibition." (PMID 37838724, 2023). "This study was closed at interim analysis, since the 2-year overall survival rate for BRAF V600 melanoma patients treated with ICI first was 72%, while the reverse treatment sequence (targeted therapy first) had a 2-year overall survival of only 52%." (PMID 37444637, 2023). "Despite tremendous advancements with BRAF-targeted therapies and immune checkpoint inhibitors, the clinical benefit of these current treatment modalities for melanoma is curbed by the almost inevitable development of resistance and tumor relapse." (PMID 36670319, 2023). "Class 2 BRAF mutations were also significantly more prevalent in HRAS (8%) compared to KRAS- and NRAS-mutant melanoma." (PMID 37503077, 2023). "These include BRAF in melanoma, RET/PDGFR in renal cell carcinoma, VEGF-A in NSCLC, MEK in melanoma and NSCLC, and PI3K in multiple cancer types." (PMID 38106415, 2023). "Moreover, the increase in HIF-1α induced by BRAF (V600E) mutation might significantly contribute to melanoma genesis in association with the PI3K/AKT/mTOR pathway, which is known to play a relevant role in early melanoma as well as resistance to BRAFi/MEKi therapy." (PMID 37895015, 2023). "While at different levels, all the PDX cells show S2R expression, regardless of their genetic background (MM13/MM16 are NRAS-mutant and MM2/MM27 BRAF-mutant melanomas)." (PMID 37298633, 2023). "Currently, BRAF-targeted therapy has been successful in significantly improving overall survival in BRAF-mutant melanomas and c-kit inhibitors have been applied in melanomas with the corresponding mutation." (PMID 37239381, 2023). "Circulating levels of BRAF, NRAS, and c-KIT mutations were assessed in 72 patients with brain metastases from melanoma and who were undergoing anti-PD1 treatment." (PMID 36835424, 2023).
melanoma (continued). "In this study, the anti-anginal drug ranolazine is found to sensitize BRAF inhibitor-resistant melanoma to targeted therapy and immunotherapy by rewiring fatty acid oxidation and the methionine salvage pathway." (PMID 37563469, 2023). "We propose a strong role for HMOX1 in metabolic plasticity and the ability of melanoma cells to switch metabolic phenotypes, as these cells adapt or initiate mechanisms to resist BRAF/MEK inhibitor treatment." (PMID 37176114, 2023). "Since BRAF V600‐mutant melanoma responded better to PD‐1/CTLA‐4 in the CheckMate 067 trial, Anti‐PD‐1 and PD‐1/CTLA‐4 should be evaluated separately." (PMID 37584204, 2023). "In the management of advanced melanoma, both BRAF/MEK targeted agents and immunotherapy are approved." (PMID 36831607, 2023). "This is based on the following considerations: (i) M238, the BRAF V600E mutant melanoma cell line used in our CRISPR screens, has a much higher expression of ERK2 than ERK1, which is also reflected in the ratio of activated levels of these proteins." (PMID 37803324, 2023). "A number of the identified markers were previously found in melanoma, including established cancer-related genes, such as BRAF or RAS." (PMID 37047539, 2023). "Using digital droplet PCR, CSF-ctDNA analysis detected BRAF and NRAS mutations in LMM and melanoma brain metastasis patients." (PMID 36980770, 2023). "In melanoma, the BRAF oncogene (serine/threonine‐protein kinase B‐Raf) is often mutated, and signalling through this pathway has been shown to confer resistance to anoikis." (PMID 38162121, 2023). "Since their approval and reimbursement, adjuvant anti-PD-1 or BRAF/MEK inhibitors have been considered the standard care treatment in resected stage III melanoma patients in the Netherlands." (PMID 36672358, 2023). "Anti‐PD‐1‐based immunotherapy is considered a preferred first‐line treatment for advanced BRAF V600‐mutant melanoma." (PMID 37584204, 2023). "The ICD-related (ICD-high and ICD-low) subgroups of patients with BRAF V600E WT melanoma were established via consensus clustering." (PMID 36704723, 2023). "Contrary to BRAF-mutant melanomas, patients with NRAS-mutant melanoma tend to be older and have chronic sun UV exposure." (PMID 37239381, 2023). "In the last years, EVs have been considered a potential source of circulating DNA to improve the detection of circulating BRAF V600E in melanoma patients." (PMID 37627054, 2023). "We recently demonstrated that peripheral blood PD-L1+ PMN frequency predicts patient prognosis and response to the anti-PD-1 agent nivolumab in patients with stage IV BRAF wild-type melanoma." (PMID 37525065, 2023). "Our study is the first study to compare the efficacy of different adjuvant setting in Stage III BRAF‐mutant melanoma including one‐third of acral subtype in real‐world practice in Chinese population." (PMID 37016119, 2023). "Roesch and colleagues use clinical datasets and mouse models of BRAF-mutant melanoma to reveal a role for IL-17A in positive responses to anti-PD-1 and anti-CTLA-4 therapy, which they also link to infiltrating neutrophils." (PMID 37525015, 2023). "Our model also postulates that the involvement of matrix metalloproteinases and EGFR signaling can contribute to the development of BRAF/MEK inhibitor resistance in melanomas." (PMID 37176114, 2023). "In the present study, we assessed the translational significance of suppressing AR signaling in the context of melanoma response to targeted drug treatments, specifically BRAF inhibitors." (PMID 37838724, 2023). "Vemurafenib has been used in clinical trials for treatment with BRAF-mutant melanoma, lung cancer, refractory or relapsed Hairy-Cell Leukemia, and other cancers as well, single or combined with other anti-cancer drugs." (PMID 37089937, 2023). "One paper reported DUSP4 deficiency leading to impaired cell proliferation and cell death in NRAS and BRAF mutant melanoma cells." (PMID 37946160, 2023).